FABP5 (fatty acid binding protein 5)
Diseases named in the same sentence as FABP5 in open-access papers (continued):
Sharing a sentence is not in itself a finding about the gene and the disease.
tumor (continued). "However, while tumor Fabp5 mRNA levels were significantly greater for chemerin-156-overexpressing mice, tumor Fabp5 protein levels were similar for both groups." (PMID 31905933, 2019). "CRABP2 has been known as the central player of RA tumor suppression, and, in contrast, FABP5 has been known as an RA tumor promotion signaling; these molecules function by delivering RA to its corresponding nuclear receptors, i.e., RAR-β and PPAR-β/δ, respectively." (PMID 29596381, 2018). "Elevated expression of FABP5 correlated with high tumor grade and poor prognosis." (PMID 29914512, 2018). "Additionally, FABP5 was stained in a total of 60 paraffin-embedded tumor sections, and the correlation between staining intensity and patient clinicopathological information was analyzed." (PMID 29914512, 2018). "Generally, co-culture with adipocytes upregulated the expression of FABP5 in tumor cells to ensure efficient FA transportation to provide substrate for downstream applications, either oxidation and energy supply, or to participate in signaling, like inducing EMT, as discovered in this study." (PMID 29914512, 2018). "Together these results suggest that FABP5 might play a crucial role in tumor progression, invasion and metastasis in HCC." (PMID 28374947, 2017). "FABP5 positivity correlated with the histologic presence of microvascular invasion (P = 0.0001), tumor differentiation (P = 0.0337), tumor size (P = 0.0001), tumor markers such as AFP (P = 0.0022) and PIVKA‐II (P = 0.0025)." (PMID 28374947, 2017). "Moreover, the role of FABP5 in promoting tumor metastasis was supported by the in vivo experimental metastasis assay, and reverse effects were observed upon knockdown of FABP5." (PMID 28374947, 2017). "Our findings suggest that FABP5 could play a crucial role of tumor progression, invasion and metastasis in HCC through EMT induction." (PMID 28374947, 2017). "FABP5 may also play a role in stimulating tumor progression by transferring ligands to nuclear PPARβ/γ27." (PMID 28211531, 2017). "Furthermore, FABP5 overexpression was correlated with tumor size, vascular invasion, poor differentiation, advanced UICC stage, and distant metastasis." (PMID 28374947, 2017). "FABP5−/− mice orthotopically injected with PyMT cells exhibited significantly less tumor volume (P=0.04), significantly slower tumor growth (P=0.035) and smaller tumor weights (P<0.05) compared to wild-type controls." (PMID 25779666, 2015). "FABP5−/− mice had a slight decrease in tumor growth compared to WT control." (PMID 25779666, 2015). "We have established host FABP5 as necessary in primary tumor development and metastasis." (PMID 25779666, 2015). "We showed that FABP5 in TNBC tumor cells is important for motility and metastasis." (PMID 25779666, 2015). "We showed FABP5 in the tumor micronenvironment is important for tumor growth and metastasis." (PMID 25779666, 2015). "In our data, the FABP5 protein was also aberrant expressed in some tumor cells of SeCC cases." (PMID 26503156, 2015). "Furthermore, FABP5 may contribute to inflammatory responses in tumor cells by modulating the expression of interleukin‐1 (IL‐1), IL‐6, and IL‐8, as well as parathyroid hormone‐related protein." (PMID 40178066, 2025). "In addition to its direct effects in pNEN cells, FABP5 can influence tumour progression indirectly." (PMID 41149452, 2025). "Additionally, FABP5 is closely associated with tumor-related signaling pathways, such as PPAR-γ, NF-κB, and IL-6/STAT3, and may promote tumor progression and metastasis through these pathways." (PMID 40717587, 2025). "Moreover, FABP5 is reported to accelerate tumor metastasis via regulation of MMP9 and MMP230." (PMID 37416772, 2023). "Moreover, in line with in vitro results, ALKBH5 over-expression led to the higher rate of tumor formation in subcutaneous xenograft models of QGP-1 cells, proved by the higher tumor weight and volume, which could also be rescued by FABP5 knockdown." (PMID 37858219, 2023).
tumor (continued). "The positive relationship between FABP5 expression and all of those four immune checkpoints in BRCA, BRCA-LumA, KIRP, LIHC, PAAD, PCPG, THCA and UVM reflected that FABP5 may interact with those four immune checkpoints to participate in tumor occurrence and development." (PMID 36906605, 2023). "We speculated that FABP5 serves as a tumour promoter in BCa." (PMID 36168624, 2022). "Furthermore, silencing FABP5 resulted in a significant decrease in tumour volume and weight." (PMID 36168624, 2022). "Therefore, the proportion of FABP5/CRABPII determines whether RA inhibits cell proliferation via the CRABPII/RAR signaling or facilitates tumor progression via the FABP5/PPARδ pathway." (PMID 35445019, 2022). "Furthermore, our studies indicate an important and novel role for FABP5 in the host and the tumor cell and that targeting FABP5 may prove a viable target to attack EGFR-enhanced TNBC metastasis." (PMID 25779666, 2015). "In addition, the expression of FABP5 protein was increased in highly proliferating tumor cells." (PMID 25797252, 2015). "Collectively, these results confirm that FABP5 knockout rewires the tumor immune microenvironment and enhances RFA‐mediated anti‐tumor immune responses in HCC." (PMID 40956367, 2025). "Mechanistically, FABP5 improves HIF-1α activity by inhibiting its interaction with Factor Inhibiting HIF (FIH), thereby enhancing lipid accumulation and tumor cell proliferation." (PMID 41357200, 2025). "In addition, FABP5 could promote tumor progression by activating PI3K/Akt/mTOR signaling." (PMID 39871325, 2025). "Mechanistic studies revealed that nanocarrier‐mediated FABP5 knockout promoted RFA‐induced ferroptosis by elevating iron ion accumulation and lipid peroxidation, processes that drive tumor cell death and suppress proliferation." (PMID 40956367, 2025). "Across multiple studies, FABP5 is consistently reported to be overexpressed in CRC tissues and cell lines, with elevated expression correlating with increased tumour cell proliferation, migration, and invasiveness." (PMID 41149452, 2025). "Clinical data analysis further confirms the key role of FABP5 in HCC, where its high expression in tumor tissues is significantly correlated with poor patient prognosis." (PMID 41035647, 2025). "Patient #6 showed low FABP5 expression level in the tumor; later we found that its VHL was wild type, which suggested that FABP5 expression is possibly related with HIF pathway." (PMID 40391655, 2025). "Histological examination further confirmed a decreased tumor burden and reduced infiltration of M2 macrophages (CD163 and F4/80 double-positive cells) in FABP5 knockout tumors." (PMID 41035647, 2025). "This strategy leverages the synergistic effects of FABP5 targeting, RFA, and immune checkpoint blockade to achieve enhanced tumor suppression." (PMID 40956367, 2025). "FABP5 activates signaling pathways such as PPARβ/δ, EGFR, and CaMKII, enhancing tumor cell proliferation, invasion, and chemoresistance." (PMID 40717587, 2025). "While the reductions in tumor volume and weight were greater in group combining MELK knockdown with RFA treatment, FABP5 overexpression prevented the enhanced effect of the combined treatment." (PMID 39871325, 2025). "In summary, these results highlight that nanocarrier‐mediated FABP5 targeting significantly enhances RFA‐induced ICD and activates DC‐mediated immune responses, thereby amplifying anti‐tumor efficacy in HCC." (PMID 40956367, 2025). "Herein, FABP5 was identified as a novel substrate of USP14, which contributes to tumor formation by maintaining the stability of oncoproteins." (PMID 39928282, 2025). "FABP5 binds to HIF-1α, promoting its nuclear translocation, thereby enhancing fatty acid metabolism and tumor cell survival." (PMID 40717587, 2025). "This secretion triggers a miR-4488/RTN3/FABP5/MMP2 feedback loop in pNEN cells, highlighting a complex interplay between pNEN cells and the tumor microenvironment that promotes tumor progression and metastasis." (PMID 38904015, 2024).
tumor (continued). "An isomer of FABP4, FABP5, secreted by HCC tumor cells both in vitro and in vivo, promotes angiogenesis." (PMID 38927059, 2024). "In tumours, both AMɸ and AIMɸ upregulated genes involved in cholesterol and lipid transport and metabolism (such as ABCA1, APOC1, APOE, FABP3 and FABP5) compared to the background tissue." (PMID 38782901, 2024). "Consistent with the observed reduction in surface FABP5 expression, CD8+ T cells infiltrating these tumor locations also demonstrated major defects in fatty acid uptake over time." (PMID 38168227, 2023). "At the same time, that of FABP5, SCD, and CCL20 were upregulated considerably in TCGA HCC compared with non-tumor tissues." (PMID 36950134, 2023). "Within the tumor microenvironment of HCC, FABP5 fosters lipid accumulation in monocytes/macrophages, modifies programmed death-ligand 1 (PD-L1) expression in regulatory T cells, and promotes immune tolerance." (PMID 37576389, 2023). "As few reports have explored the function of FABP5 in CRC, we initially established a tumor microarray using 90 CRC and peri-tumorous tissues." (PMID 37416772, 2023). "The administration of this natural product inhibited tumor growth by downregulating PPARα, PPARγ, FABP1, FABP4, and FABP5." (PMID 36296934, 2022). "Recent studies in triple-negative breast cancer (TNBC) have proved that decreasing the proportion of FABP5/CRABPII in breast tissue converts RA from PPARβ/δ to RAR, thereby suppressing tumor growth." (PMID 35445019, 2022). "Comparison of genes differentially expressed between the subcluster C9 of exhausted CD8+ cells from tumors and normal tissues showed GNLY and ITM2A were highly expressed in normal tissues, and high expression of FABP5 and RPS6 was exhibited in tumor tissues." (PMID 35874785, 2022). "We examined FABP5 expression in 48 paired HCC tissues and adjacent normal tissues using qPCR and consistently found that it was significantly upregulated in the tumor tissues." (PMID 35816613, 2022). "But our team deemed that it is related to tumor types and specific pathological types, and the expression level and ratio of CRABP2 and FABP5 are expected to serve as valuable biomarkers." (PMID 34632074, 2021). "A recent study showed that tumor cells also upregulate FABP4 and FABP5 expression and outcompete tumor reactive CD8 TRM cells for lipid uptake leading to TRM cell death." (PMID 33922441, 2021). "We also show that specific inhibitors of FABP4 and FABP5 and the plant-derived galactolipid, dLGG, inhibit the metastatic phenotype in TNBC cells and in tumor inoculated animals." (PMID 31941087, 2020). "Our results showed that areas of FABP5 staining overlapped with areas of CA9 staining, suggesting that hypoxic areas in these tumours strongly expressed FABP5." (PMID 32550890, 2020). "FABP5, IVL, KRT6A, KRT15, KRT16, and TIMP2 expression profiles suggested relatively significant elevated expression in tumor tissues compared with the corresponding normal tissues." (PMID 32934956, 2020). "We found that the mRNA expression levels of FABP5, FASN, HSL, TWIST1, VEGF-C, and MMP9 were significantly higher in tumours of the bevacizumab group than those of the control group." (PMID 32550890, 2020). "FABP5 also facilitates the generation of fatty acids through lipolysis of lipid droplets (LDs) and de novo fatty acid synthesis to promote TNBC tumor progression." (PMID 32296646, 2020). "We then examined the levels of Ki67, FABP4, FABP5, and CYP2C19 in tumor and lung tissues by IHC staining." (PMID 31941087, 2020). "Similar to FASN-overexpressing cells, we did observe larger tumor mass of MAGL-overexpressing cells relative to vector-expressing cells ex vivo, which was suppressed upon FABP5 knockdown." (PMID 31831821, 2019). "The correlation between overexpression of fatty acid‐binding protein 5 (FABP5) and malignant potential of tumor growth and metastasis in several cancers has been previously reported." (PMID 28374947, 2017).
tumor (continued). "In particular, CRABP1 was expressed in the tumor stroma, and CRABP2 and FABP5 were expressed in the sebaceous gland cells, interfollicular epidermis, and hair follicles." (PMID 26503156, 2015). "CRABP2 and FABP5 were expressed in hair follicles of eyelid skin in both groups, whereas CRABP2 and FABP5 were aberrantly expressed in the SeCC tumor cells." (PMID 26503156, 2015). "Five potential novel target genes (FABP5, CD24, CD44, CD74, and HSP27) were identified, which were highly expressed in HNSCC tumor samples and tissue arrays." (PMID 19602232, 2009). "Drugs that inhibit fatty acid oxidation or interfere with lipid signaling pathways, such as inhibitors of ALOX5AP or FABP5, could serve as potential therapies for GBM by impairing the metabolic fitness of TAMs and reactivating anti-tumor immunity." (PMID 41164132, 2025). "A significant reduction in the proportion of proliferative CD8+ T cells was observed in the FABP5‐positive group compared to the FABP5‐negative group, indicating a more robust anti‐tumor immune response in the FABP5‐negative cohort." (PMID 40956367, 2025). "Following FABP5 inhibition via nanocarriers, C11‐BODIPY fluorescence assays revealed a significant increase in lipid peroxidation and a corresponding decrease in GPX4 expression in tumor cells, indicating that FABP5 inhibition enhances RFA‐induced ferroptosis." (PMID 40956367, 2025). "Most notably, in vivo experimental data are currently lacking to confirm whether ICT can similarly modulate the expression of CA9, UCK2, FABP5, and CYP2C9, as well as remodel the tumor immune microenvironment in living organisms." (PMID 41357200, 2025). "Correspondingly, FABP5-KO tumors displayed diminished intratumoral lipid droplet accumulation (BODIPY staining), suggesting a reduction in lipid metabolism damage within the tumor microenvironment." (PMID 41035647, 2025). "Nanocarrier‐mediated FABP5 deletion was found to promote RFA‐induced ferroptosis and anti‐tumor immune responses, including increased infiltration of CD8+ T cells and effector memory T cells, through activation of the STING/TBK1 pathway and stabilization of TBK1 protein." (PMID 40956367, 2025). "Furthermore, FABP5 deletion potentiates RFA‐induced ferroptosis and bolsters anti‐tumor immune responses, characterized by increased infiltration of CD8+ T cells and effector memory T cells, contributing to pronounced systemic anti‐tumor effects." (PMID 40956367, 2025). "FABP5 enhances tumour cell proliferation and migration via pathways including PI3K/AKT/mTOR and cAMP response element-binding protein (CREB)-mediated miR-889-5p signalling, which targets and suppresses the tumour suppressor Kruppel-like factor 9 (KLF9)." (PMID 41149452, 2025). "To ensure that miR-4488, RTN3, and FABP5 do not independently affect the expression of MMP2 in tumor cells, we conducted Western blot experiments." (PMID 38904015, 2024). "At present, there has been no report about the potential miR-22-3p-FABP5 relationship in any tumor type available." (PMID 36906605, 2023). "We further examined the roles of FABP5 and FASN in vivo with the aid of tumor xenograft models." (PMID 37416772, 2023). "Intriguingly, the EVs secreted by invasive tumoroids (3D d10‐d14) contained several unique proteins promoting tumour growth and invasion, for example, SLC4A7, SLC12A2, FABP5, PRDX1, CD59 and CD73, showing that specific oncogenic signals are loaded in EVs upon invasion." (PMID 38938900, 2023). "Thus, we performed RNAscope staining and detected a coexpression pattern of FABP5, NME1, and MKI67 across the tumor tissues." (PMID 37402315, 2023). "In addition to FABP5, tumor microenvironment (TME), which is composed of stromal cells, immune cells and tumor cells, also makes great contributions in the tumorigenesis and progression." (PMID 36906605, 2023). "However, in tumor tissues, C1QC + macrophages receive CSF signaling from both MFAP5 + and FABP5 + fibroblasts, suggesting an immunomodulatory role in CRC." (PMID 37344903, 2023).
tumor (continued). "Although the potential oncogenic role of FABP5 has been confirmed in multiple tumor types, there is a lack of more comprehensive analyses about FABP5 and corresponding molecular mechanism." (PMID 36906605, 2023). "FABP5 may therefore be of significant clinical value in CRC, since this tumor type is closely related to lipid metabolism." (PMID 37416772, 2023). "Thus, our data show that murine tumor-derived RCaP cells, which are ADT and taxane resistant, are sensitive to TAME-based FABP5 inhibitors." (PMID 38201488, 2023). "FABP5, the most widely expressed FABP, is detectable in the epidermis, liver, kidney, lung, adipocytes, brain, and mammary gland and is related to tumor progression through activation of peroxisome proliferator-activated receptor signaling." (PMID 35721518, 2022). "In addition, FABP4 secreted by CAA actively transports FA to tumor cells and the elevated expression of the FA transport proteins such as CD36 and FABP5, leading to an amplified transport of FA to tumor cells and boosting their proliferation." (PMID 36551752, 2022). "What makes us feel contradictory and interesting is that FABP5 should be a tumor suppressor in ESCC like CRABP2, with high expression in normal tissues and low expression in tumor tissues." (PMID 34632074, 2021). "GSEA results showed LGG tumors with high expression of CD302 or FABP5 enriched JAK/STAT and ECM receptor interaction signaling pathway, which are reported to be involved in tumorigenesis and could promote tumor progression." (PMID 32775301, 2020). "Enrichment of FABP/EET-source cells, for example, adipocytes and monocytes, in the metastasis niche, can be one method by which distal homing of FABP5-deprived cancer cells occurs, even in the absence of the primary tumor (tumor resection model)." (PMID 31941087, 2020). "Moreover, LGG tumors with CD302 or FABP5 overexpression highly expressed some oncogenes, including GPR65, PIK3CG, CHI3L1, and RAB36, which were reported to promote tumor growth and metastasis." (PMID 32775301, 2020). "Our data showed that FABP5 protein expression was significantly higher in CCa tumours with LNM than in those without LNM and in NCTs." (PMID 32550890, 2020). "Importantly, inhibition of FABP5 dramatically repressed LNM in vivo and prolonged the survival times of tumour-bearing mice." (PMID 32550890, 2020). "Consistently, knockdown of FABP5, SP1 or both could all abolish the tumor-promoting effected induced by PA to similar extent." (PMID 30948929, 2019). "Similarly to FABP5, CRABP1 is also preferentially expressed in ER- and TNBC tumor tissues that are prone to ATRA resistance." (PMID 30384831, 2018). "Therefore, it is of high significance for treatment of inflammation, metabolic diseases, and inhibiting of tumor growth to develop new dual inhibitors with good pharmacokinetics and biochemical characteristics to target FABP4 and FABP5." (PMID 30142969, 2018). "However, as FABP5 knockdown resulted in suppression of cell proliferation along with AMPK activation (T172 phosphorylation), AMPK seems to function as a tumor suppressor in PCa cells." (PMID 30167092, 2018). "In parallel with the expression pattern in tumor cells, FABP5 was not expressed in normal breast tissues, but in cancerous specimens." (PMID 29914512, 2018). "This suggests that redirection of atRA through FABP5 to PPARβ/δ is not a predominant mechanism for the promotion of tumor growth and proliferation by atRA in our model." (PMID 29192143, 2017). "In conclusion, CRABP-II and FABP5 expression patterns are neither related to the tumor grades nor correlated with RA sensitivity." (PMID 25797252, 2015). "FABP5 protein expression is highly expressed in high tumor grades as well as TNBC samples, which has not been previously shown." (PMID 25779666, 2015).